SHISA2 (shisa family member 2)
Description:
Plays an essential role in the maturation of presomitic mesoderm cells by individual attenuation of both FGF and WNT signaling.
Synonyms: C13orf13; TMEM46; bA398O19.2; PRO28631; WGAR9166; hShisa
Tractability: Antibody: UniProt predicts a signal peptide or a membrane-spanning region.
Gene: Protein-coding gene on chromosome 13 (26,044,597 to 26,052,016, reverse strand). Ensembl gene ENSG00000180730.
Subcellular location: Endoplasmic reticulum membrane
Subcellular location (Human Protein Atlas): Nucleoplasm; Nuclear bodies; Vesicles
Gene Ontology:
Molecular function: protein binding
Biological process: negative regulation of fibroblast growth factor receptor signaling pathway; negative regulation of Wnt signaling pathway
Cellular component: endoplasmic reticulum; endoplasmic reticulum membrane
Genetic constraint (gnomAD): Loss-of-function variants: 16 observed, 18.27 expected, observed/expected ratio (o/e) 0.88, 90% interval 0.59 to 1.33. The synonymous counts are far from expectation, so gnomAD's model fits this gene poorly and the ratio says little. Missense variants: 459 observed, 371.3 expected, observed/expected ratio (o/e) 1.24, 90% interval 1.14 to 1.34. Synonymous variants: 201 observed, 158.9 expected, observed/expected ratio (o/e) 1.26, 90% interval 1.13 to 1.42.
Homologues: Orthologues: chimpanzee SHISA2 (99% identical), macaque SHISA2 (99% identical), rabbit SHISA2 (96% identical), dog SHISA2 (94% identical), mouse Shisa2 (93% identical), rat Shisa2 (93% identical), pig SHISA2 (92% identical), guinea pig SHISA2 (86% identical), tropical clawed frog shisa2 (78% identical), zebrafish shisa2b (59% identical). Paralogues in human: SHISA3 (39% identical), SHISA4 (17% identical), SHISAL1 (13% identical), SHISAL2A (11% identical), SHISAL2B (10% identical).
Diseases named in the same sentence as SHISA2 in open-access papers:
SHISA2 is named in the same sentence as 14 diseases in open-access papers, as found by Europe PMC text mining. Sharing a sentence is not in itself a finding about the gene and the disease. The quoted sentences say what the papers report.
bladder cancer (1 paper, 2021). "While CNN3, SHISA2, TMED3, SRGN were downregulated in persistently infected bladder cancer cells." (PMID 34044804, 2021).
hepatocellular carcinoma (1 paper, 2015). A malignant tumor that arises from hepatocytes. "SHISA2 was also expressed at higher level in hepatocellular carcinoma (n = 39) as compared to NAT (n = 13) (P < 0.001)." (PMID 26427334, 2015). "Surprisingly, normal tissue (n-17) gave high expression of SHISA2 compared to NAT (p < 0.001) and differences with hepatocellular carcinoma were not significant." (PMID 26427334, 2015).
medullary carcinoma (1 paper, 2015). "In medullary carcinoma SHISA2 high expression was observed in 7 out of 9 patients tissues as compared to NAT (P = 0.084)." (PMID 26427334, 2015).
nasopharyngeal carcinoma (1 paper, 2024). A carcinoma arising from the nasopharyngeal epithelium. "Three hub genes (EME1, WNT4, SHISA2) show strong correlation with m6A regulators and elevated levels of methylation modifications in nasopharyngeal carcinoma tissues." (PMID 39726587, 2024).
prostate adenocarcinoma (1 paper, 2015). "SHISA2 staining in prostate adenocarcinoma confirms previous observations of SHISA2 activation in prostate aggressive cancer." (PMID 26427334, 2015).
prostate carcinoma (1 paper, 2015). A carcinoma that arises from epithelial cells of the prostate gland. "SHISA2 was reported recently to be overexpressed in high-grade prostate cancer cells and to be involved in aggressive phenotype of prostate cancer." (PMID 26427334, 2015).
cancer (5 papers, 2013 to 2025). A tumor composed of atypical neoplastic, often pleomorphic cells that invade other tissues. "Moreover, the genes HES6, SHISA2, PMP22, and IL1RL1 are primarily associated with the progression of cancer and diseases." (PMID 39336820, 2024). "To provide a proof of principle that the list of genes that are commonly hypomethylated and induced in 3 invasive cancer cell lines could serve as a source for discovery of new genes involved in invasiveness, we picked four genes, C11orf68, G0S2, SHISA2 and TMEM156." (PMID 26427334, 2015).
tumor (2 papers, 2022 to 2024). "By integrating transcriptome sequencing data, 19 m6A-modified genes were found to be upregulated in tumor tissues, leading to the development of a three-gene (EME1, WNT4, SHISA2) risk prognosis model." (PMID 39726587, 2024).
SHISA2 also shares sentences with these, for which no sentence is quoted: breast carcinoma (2 papers); gastric cancer (2); adenocarcinoma (1); asthma (1); medulloblastoma (1); Obesity (1).